MCM2 (minichromosome maintenance complex component 2)
Diseases named in the same sentence as MCM2 in open-access papers (continued):
Sharing a sentence is not in itself a finding about the gene and the disease.
tumor (continued). "Our study demonstrated that TCF3 suppressed CRC development by modulating DNA replication through repressing MCM2 and MCM5 transcription, providing a novel mechanistic insight into its tumor-suppressive function." (PMID 40998798, 2025). "The results revealed that in tumor tissues from ccRCC patients, POLQ expression positively correlated with the expression of CDC6, CDC45, CDT1, FANCD2, and MCM2." (PMID 38270643, 2024). "One cluster (C2 Tumor cells) expressed stem-related genes (SOX4 and CD164); the other (C3-Tumor cells) expressed proliferative genes (MKI67 and MCM2)." (PMID 36788228, 2023). "In our study, the expression of KLF9, MCM2, INHBA, and CGREF1 was significantly correlated with TNM clinical stage and tumor differentiation, excluding tumor location, age, and sex." (PMID 37370046, 2023). "Expression levels of MCM2 and PCNA in xenograft tumor tissues were lower in the shGBAP1-2 group than that in the NC group." (PMID 37407932, 2023). "However, overexpression of MCM2/5 could not entirely restore tumor growth arrest caused by YTHDF2 depletion, which warrants further studies to identify additional targets of YTHDF2 that participate in HBV-related HCC progression." (PMID 36765030, 2023). "To determine the clinical relevance of MCM2 or NUP37 overexpression in human HCC, we firstly investigated the correlation between tumor stage (TNM stage) and MCM2 or NUP37 overexpression using TCGA samples." (PMID 35093119, 2022). "Consistently with the expression profiles in omics datasets of HCC, validation by western blot and RT-PCR in 10 pairs of human HCC tissue samples showed that MCM2 and NUP37 were significantly upregulated in HCC relative to the paired peri-tumor samples." (PMID 35093119, 2022). "Additional members of the MCM complex (i.e. MCM2, MCM3, MCM6, and MCM7) were upregulated in all sample groups but basal-like TN tumours." (PMID 36220861, 2022). "Recent in vivo studies showed that the use of MCM2/CA9 inhibitors, such as ciprofloxacin and acetazolamide, respectively, in combination with cisplatin, improve mice overall survival and reduce tumor nodule growth." (PMID 33921816, 2021). "In conclusion, we obtained several DEGs in CC and found that overexpression of DNMT1, CHAF1B, CHAF1A, MCM2, KNTC1 in tumor tissues predicted poor survival in CC." (PMID 33616161, 2021). "Among the genes associated with the malignant stage, minichromosome maintenance complex 2 (MCM2) and carbonic anhydrase 9 (CA9) show a positive correlation with tumor growth, and these genes are potential targets for therapeutic strategy." (PMID 33921816, 2021). "Our findings suggest that MCM family members play crucial roles in BC progression, and MCM2, MCM4–7, and MCM10 in tumor tissues possess great potential to be valuable prognostic biomarkers for BC patients." (PMID 34475953, 2021). "In summary, analysis of CALU co-expressed genes network as one the key regulators in tumor metastasis introduced a gene panel that consists of CALU, AURKA, and MCM2 with high discriminative accuracy between healthy and cancer (colon and lung) populations." (PMID 32469983, 2020). "We already proved that Ki-67, MCM2, Cyclin A and PHH3 are good predictors of pCR after the PST, however, not only pCR, but also rate of partial tumor remission is prognostic for the clinical outcome." (PMID 31446607, 2020). "In summary, CDCA5, FOXM1, KIF15, MCM2, and ZWINT was involved in cell mitosis and supported our research results by affecting the cell cycle regulation of tumor pathogenesis." (PMID 31708970, 2019).
tumor (continued). "Recent studies have reported that tumor-suppressive miRNAs negatively regulate the expression of MCM family genes (e.g., MCM2 is targeted by miR-31 and MCM5 is targeted by miR-885-5p and miR-362-3p)." (PMID 31514295, 2019). "Previous studies have confirmed that MCM2, BIRC5, and RFC4 are abnormally highly expressed in HCC, and that they participate in the regulation of HCC tumor biology." (PMID 31534853, 2019). "As compared with CDCP1– cells from muKras tumor cells (DKs5 and HK2-10), the matched CDCP1+ fraction expressed lower levels of markers for cell proliferation, including Ki67, PCNA, and MCM2." (PMID 31461438, 2019). "Based on the sequencing data, four tumor differentiation related genes (JUB, HMGA2, FAM110B and MCM2) were selected to perform the expression validation by GEO database." (PMID 29596435, 2018). "MCM2, MCM6 and MCM7 proteins were expressed at significantly higher levels in HCC compared to non-tumor specimens (P < 0.01), and the degree of their immunoreactivity gradually increased from normal and cirrhotic livers to HCC." (PMID 29463213, 2018). "Five genes namely ZWINT, CDC7, MCM4, MCM2 and MCM6 are proposed from the comprehensive computational analysis which gets affected in neoplasia stage and are responsible for the disease progression." (PMID 30150654, 2018). "Markedly, cancer cells often express DNA replication factors including the MCM helicase at high levels, and MCM2 and MCM7 are considered as biomarkers and potential therapeutic targets for cervical, colorectal and other tumours (for example, refs 50, 51, 52)." (PMID 26876972, 2016). "We analyzed five patients with the tumor located at different part of the pharynx and found significant increase in cell cycle regulatory CDC20 and MCM2 genes in the tumor when compared with healthy tissue (p = 0.0467and p = 0.0438, respectively)." (PMID 25575813, 2015). "Frequent over expression of MCM10, which partners with RECQL4 and binds to MCM2-7 complex activating its helicase activity, indicates that MCM10 is critical in the tumor progression." (PMID 23874974, 2013). "Core promoters with adjacent regions of the human genes CDC6, POLD1, CKS1B,MCM2, and PLK1 were cloned into a pGL3 vector in front of the Photinus pyrailsgene Luc in order to study the tumor specificity of the promoters." (PMID 24303203, 2013). "The positive correlations between mitotic counts, Mcm2 PIs, and Ki67/MIB-1 PIs found in this study are in accordance with studies on other human tumours." (PMID 23618321, 2013). "Further studies of OSCC evaluating Mcm2, Ki67 and geminin expression, along with their Mcm2/Ki67 and geminin/Ki67 LI ratios, may provide further evidence of their prognostic potential, especially if they can be correlated with mode of invasion, tumour size and cumulative disease-free survival." (PMID 19293805, 2009). "The median MCM-2 and MCM-5 LIs were significantly higher in adenocarcinomas (20 and 24%, respectively) compared to LMP tumours (5 and 6%, respectively) (Mann–Whitney U-test, P<0.0001 for both associations)." (PMID 17940502, 2007). "The Cuzick extension of the Wilcoxon's rank sum test confirmed the presence of a significant trend of increasing MCM-2 and MCM-5 expression with increasing tumour stage (P=0.0100 and 0.0300, respectively)." (PMID 17940502, 2007). "From these results, we speculated that activation of the MAPK pathway and elevated MCM2 expression may drive the aggressive phenotype of c‐Myc‐positive TNBC, whereas co‐targeting c‐Myc and Ras signalling with Salirasib may suppress tumour progression." (PMID 41020311, 2025). "In addition, ETV4 transcriptionally controls the key replisome genes MCM2, ‐4, ‐5, ‐10, and ORC1 expression and affects tumor growth and prognosis of NSCLC patients." (PMID 40548893, 2025).
tumor (continued). "In summary, TRIM21 could influence tumor development and chemosensitivity to replication inhibitors by regulating DNA replication through the TCF3/MCM2/5 axis, suggesting a promising potential for CRC in the clinic." (PMID 40998798, 2025). "The HPV-positive-related subtype also exhibited higher expression in tumor growth, and some studies have indicated that HPV virus may dysregulate the cell cycle to promote cancer cell growth (e.g., CDK4 and MCM2, both members of HNSC88)." (PMID 37685875, 2023). "Finally, we verified that the expression levels of KLF9, MCM2, INHBA, and CGREF1 were related to age, tumor stage, and differentiation and were closely related to the prognosis of young CRC patients." (PMID 37370046, 2023). "High expression of MCM2 was reported to be positively correlated with Ki67 in various malignant tumors, such as CRC, which indicates its crucial carcinogenic role in promoting tumor proliferation." (PMID 37370046, 2023). "Similarly, the MCM2 and NUP37 protein levels in HCC tissues are significantly higher than that in peri-tumor tissues from NODE proteomics dataset." (PMID 35093119, 2022). "In addition, PLA2 knockdown suppressed MCM2 expression and increased the γ‐H2AX protein level in tumour tissues." (PMID 35166019, 2022). "Although AS4583 was found to induce the degradation of MCM2 by ubiquitination, the anti-tumor mechanism, safety, and efficacy have not been reported." (PMID 36303105, 2022). "In MHCC-97H and HUH-7 cells, suppression of MCM2 significantly restrained the formation of tumor spheroids, and thus the probability of negative responses increased in the knockdown group." (PMID 36243809, 2022). "The expression of MCM2 and MCM3 in EC is correlated with the strong proliferation ability of tumor cells, suggesting that MCM2 and MCM3 may be involved in the proliferation of EC." (PMID 34859821, 2021). "In this sense, we also acknowledge that potential dysregulation of inflammation-related genes included in our proposed molecular signature (e.g., IL1A, MCM2, MMP1, MMP12, and VEGFA) might be due to the inflammation favoring tumor maintenance and progression." (PMID 34638231, 2021). "Moreover, we validated the overexpression of MCM2 and MCM4 in NSCLC by using the fresh samples from 30 patients who had undergone tumor removal surgery in our hospital." (PMID 33936158, 2021). "MCM2 and VEGFA, also targets of miR-145-5p, were overexpressed in our tumor samples." (PMID 34638231, 2021). "Compared with other genes, MCM2, TOP2A, CDC45, KNTC1, RFC4 and RMI2 were highly expressed in CESC tumor tissues and might be better indicators of prognosis." (PMID 34174849, 2021). "Indeed, we here show that, in vivo, the pharmacological inhibition of MCM2 and/or CA9 is efficacious to inhibit/block tumor growth, thus representing a novel promising therapeutic strategy." (PMID 33153038, 2020). "The increase in MCM2, MCM3, and MCM6 is related to poor performance of the tumor." (PMID 33234725, 2020). "To further confirm the field effects of p‐STAT3, Mcm2 + luminal to basal ratio, and MSR1 + cell number, we detected the immunoreactivity of the p‐STAT3 and MSR1 + cell number in the PCa, pericancer tissues near and far from tumor core, and benign tissues." (PMID 32860339, 2020). "First, in order to assess whether a correlation between the expression of MCM2/CA9 genes and the growth rate of the tumor mass exists, we took advantage of a mouse model of subcutaneously injected NB tumor xenograft, using SKNBE2 cells." (PMID 33153038, 2020). "Our results agree with the observations that MCM2, MLH1 and ERCC1 may serve as an oncogene and that PARP1 may function as tumor suppressors genes during tumorigenesis." (PMID 31598158, 2019). "MP-HX downregulated the expression of genes that could promote anti-apoptotic effect, cell cycle progression, tumor development and progression, which include BIRC5, CCNA2, CCNB1, CCNB2, CCNE2, CDK1/2/6, GINS2, HELLS, MCM2/10 PLK1, RRM2 and SKP2." (PMID 30042885, 2018).
tumor (continued). "Immunohistochemical stainings of cyclin E, MCM2, VEGF, CDC6 and BCL2 were performed in tumor tissues, and the staining intensities of cyclin E, MCM2, CDC6 and BCL2 were decreased in the GBK treatment group in xenograft-tumor mice compared to the control group." (PMID 28467790, 2017). "TTK, MCM2, CLDN7 and TSPAN13 promote tumor cell proliferation and their overexpression could stimulate drug resistance." (PMID 26515599, 2015). "Because of this role, the MCM protein family (MCM2 to MCM7) consists of important histological markers to determine cell replication and thus, together with Ki-67, determines prognostic factors in various neoplasms." (PMID 26823641, 2015). "In contrast, nonproliferating tumor cells subjected to enough stimuli to initiate new proliferation would present an immunoexpression pattern negative for Ki-67 and positive for MCM2 and MCM3." (PMID 26823641, 2015). "Aside from MCM2, the suppressive effect of miR-31 on NPC tumor growth was also via repressing FIH1." (PMID 25098679, 2014). "We found a significant increase in MCM2 (3.5 fold), MCM3 (3.1 fold), MCM4 (4.3 fold), MCM5 (3.8 fold), MCM6 (3.5 fold), MCM7 (3.0 fold) and MCM10 (3.6 fold) expressions in tumor tissues (the average fold value of three grades) compared to the normal brain controls." (PMID 25046975, 2014). "The average expression level of MCM2 does not show any significant difference in different tumor stages." (PMID 23874974, 2013). "The discrepancy of correlation of MCM2, MCM5 and MCM7 may be due to a very small sample size in tumor stage I (N = 06)." (PMID 23874974, 2013). "The Kruskal-Wallis test revealed that there were statistically significant overall correlation of MCM2 levels with lymph node status (p = 0.007) and clinical stage (p = 0.002), but not with histological grade (p = 0.84) or tumor size (p = 0.127)." (PMID 19116018, 2008). "In summary, expression of Mcm2 in ≥40% of tumour cells was found to be a negative prognostic marker for disease specific survival in this large series of DLBCL." (PMID 16368013, 2005). "As in the case of well-differentiated tumours, normal breast has a similarly high Mcm2/Ki67 ratio (median: 11.16) indicative of a licensed nonproliferating state." (PMID 16278669, 2005). "Mcm2 expression was clearly evident in the nuclei of proliferating non-neoplastic cells and tumour cells." (PMID 16368013, 2005). "Disease specific survival was compared between tumours positive and negative for Mcm2 by univariate log-rank statistics." (PMID 16368013, 2005). "Mcm4D573H could not alter the total expression of MCM2‐7 complex, whereas it significantly promotes tumor formation." (PMID 36776764, 2023). "However, the MCM2-dependent parental histone segregation pattern in cancer cells, as well as its role during tumor progression has not been investigated yet." (PMID 37301892, 2023). "The prognosis is favourable for GC patients whose tumours do not exhibit MCM2." (PMID 37594635, 2023). "Interestingly, in comparison with other CpG sites in promoter region, cg08889930, an enhancer of MCM2 gene, located at CpG island shores, with a mean betavalue > 0.6, was obviously hypermethylated in both tumor and paired nontumor samples." (PMID 35093119, 2022). "The mRNA expression profiles of MCM2 or NUP37 stratified by the tumor stage showed that MCM2 (Stage II vs. Stage I, p < 0.05; Stage III vs. Stage I, p < 0.001) or NUP37 (Stage II vs. Stage I, p < 0.05; Stage III vs. Stage I, p < 0.05) expression was significantly increased in advanced tumor stage." (PMID 35093119, 2022). "Higher Olig2 and GFAP/MCM2 densities in FCD3b may reflect margins of the tumour infiltration zone rather than true cortical dysplasia." (PMID 33370704, 2021). "Obviously, the down-regulation of miR-1296 in A2M*-treated cells may not follow the overall anti-tumour activity of A2M* as this miR is known to up-regulate oncogene MCM2." (PMID 29281661, 2017).
tumor (continued). "In addition, we measured the expression of a number of other genes in the tumours including nuclear receptors (VDR, RXRα, SXR, ER α and β), cytochrome P450 enzyme (CYP3A4), proliferation marker (MCM2, CDC6, KI67), differentiation marker (sucrase isomaltase) and angiogenesis marker (CD31)." (PMID 26238339, 2016). "However, an assessment of MCM2 and MCM3 expression would be useful to predict tumor behavior." (PMID 26823641, 2015). "Therefore, MCM2 and MCM3 may be used as predictive markers of more aggressive tumor behavior and potentially as important markers to predict the risk of malignant transformation." (PMID 26823641, 2015). "Similarly to MCM2, MCM3 has been studied in different neoplasms." (PMID 26823641, 2015). "Therefore, it is possible to suggest that high expression of MCM2 and MCM3 may be a more reliable marker of proliferation than is Ki-67 in assessing tumor growth and evaluating the potential for recurrence." (PMID 26823641, 2015). "MCM2 is over expressed irrespective of tumor lesion types (data not shown)." (PMID 23874974, 2013). "In most cases (37/43 genes), methylation was more frequent in cell lines than primary tumours, however for 6 genes this pattern was reversed (ZNF215: 21% and 42% respectively, DAPK1: 4% and 39%, EPHA3 13% and 32%, SMARCB1: 8% and 27%, EPS8 4% and 21% and MCM2: 0% and 21%)." (PMID 19493342, 2009). "Furthermore, there was a statistically significant link between high ERK5 expression and increased Mcm2-Ki67 (P=0.01), signifying an increase in the proportion of non-cycling tumour cells that are licensed for replication." (PMID 17406359, 2007). "Consequently, MCM2 and MCM3 may help to predict tumor behavior." (PMID 26823641, 2015). "Importantly while a clear relationship between Mcm2 protein expression and Gleason grade has been shown in this study, high Mcm2 expression does not preclude the possibility of low Gleason grade, indicating a broad spectrum of growth potential within each tumour grade." (PMID 17406359, 2007). "Immunohistochemical staining of fixed tumour tissues revealed non-significantly reduced levels of proliferative marker, MCM2, in ASO-361-3p-treated tumours vscontrols, but no change in cleaved PARP protein levels." (PMID 36622663, 2023). "Notably, we found that KLF9 and INHBA were associated with prognosis in EOCRC but not in LOCRC, while the expression differences in KLF9, MCM2, and INHBA between the tumor and normal groups were more obvious in EOCRC than in LOCRC." (PMID 37370046, 2023). "Interestingly, the differential expression plot across tumor types also shows CIZ1 expression is not much different between tumors and their normal tissues quantitatively, unlike MCM2 for example supporting the concept of possible predisposition." (PMID 30107825, 2018). "Although there are no available AM studies with MCM2 and MCM3, predicting tumor behavior could be supported by statistical significance between the expression of MCM2 and MCM3 versus Ki-67 in histological subtypes." (PMID 26823641, 2015). "This study evaluated whether a nonproliferative tumor cell phenotype, P21 (CDKN1A inhibitor)-positive and MCM2 (DNA replication protein)-negative (P21+/MCM2-), could serve as a robust biomarker to improve prognostic stratification and guide postnephrectomy treatment decisions." (PMID 41990272, 2026). "Lastly, the proliferation marker MCM2 did not significantly change following double knock out of SAA1/2 in vivo, however, the inhibition of autophagy with CQ significantly increased the expression of MCM2 in the SAADKO group when compared to the untreated WT and SAADKO tumor groups." (PMID 36248994, 2022).